DKK1 (dickkopf Wnt signaling pathway inhibitor 1)
Diseases named in the same sentence as DKK1 in open-access papers (continued):
Sharing a sentence is not in itself a finding about the gene and the disease.
rheumatoid arthritis (35 papers, 2010 to 2025). A chronic, systemic autoimmune disorder characterized by inflammation in the synovial membranes and articular surfaces. "The treatment of ankylosing spondylitis and rheumatoid arthritis with TNF-α inhibitors was associated with a concurrent decrease in the DKK1 serum levels." (PMID 35393522, 2022). "We previously demonstrated increased DKK-1 level in the French cohort ESPOIR of rheumatoid arthritis and associated with increased risk of radiographic progression." (PMID 26313358, 2015). "Most importantly, DKK1 positively correlated with erosive bone loss in patients with rheumatoid arthritis, supporting a central role for this factor in inflammatory bone loss." (PMID 23079210, 2012). "However, Dkk-1 is implicated in bone destructive phenotypes and osteoclast activation that characterize autoimmune joint diseases such as rheumatoid arthritis." (PMID 35281012, 2022). "For instance, PRF serum up-regulated genes such as CCNE2 and CDC25A linked to the cell cycle, as well as DKK1, a WNT-signaling antagonist with a potential impact on inflammatory osteolysis in rheumatoid arthritis and in periodontitis." (PMID 39120336, 2024). "Serum osteocalcin (OSC) and Dickkopf-related protein 1 (DKK-1) were found to be higher in patients with rheumatoid arthritis, OPLL, and ossification of the ligamentum flavum." (PMID 37509659, 2023). "DKK‐1 has been found to be dysfunctional in AS patients in comparison with rheumatoid arthritis (RA) patients and healthy control group." (PMID 37506134, 2023). "The overexpression of both Dkk1 and Bmi1 was found to be related to cytokine‐cytokine receptor interactions, rheumatoid arthritis, renin secretion, and nitrogen metabolism in our study." (PMID 33639034, 2021). "Blockage of DKK-1 with anti DKK-1 antibody has been shown to increase bone formation in a mouse model of rheumatoid arthritis." (PMID 28275825, 2017). "We investigated the role of Dickkopf-related protein 1 (DKK1) produced by synovial fibroblasts of patients with very early rheumatoid arthritis (VeRA)." (PMID 26782930, 2016). "Since Dkk1 inhibition has further been shown to attenuate erosive bone destruction in a mouse model of rheumatoid arthritis, it is highly relevant that Dkk-1 antibodies are under evaluation in clinical studies." (PMID 26056589, 2014). "In other studies, elevated levels of the WNT pathway antagonists sclerostin and DKK1 were reported in animal models of rheumatoid arthritis." (PMID 24618907, 2014). "Expression of sclerostin and DKK1 was elevated in synovial tissue from rheumatoid arthritis patients compared to controls and bone repair was often delayed or repressed in patients with systemic inflammatory background." (PMID 24618907, 2014). "This is consistent with the finding that etanercept is able to activate osteoblastogenesis and new bone formation by means of Dkk1 inhibition in the rheumatoid arthritis (RA) rat model." (PMID 25280749, 2014). "It has been previously demonstrated that circulating Dkk-1 is present in rheumatoid arthritis, ankylosing spondylitis, and osteoarthritis." (PMID 21062498, 2010). "In addition, hsa-miR-218-5p induces osteogenic differentiation of rheumatoid arthritis synovial fibroblasts by regulating ROBO1/DKK-1 pathway." (PMID 37525657, 2023). "In support of this notion, it has been suggested that bone formation is often repressed in patients suffering from rheumatoid arthritis and that DKK1 and sclerostin (inhibitors of bone formation) were detected in serum of these patients and other inflammatory conditions." (PMID 24618907, 2014). "In addition, Diarra and colleagues have documented that blockade of Dkk-1 reverses the bone-destructive pattern in a mouse model of rheumatoid arthritis to the bone-forming pattern of OA, indicating that Dkk-1 is a central regulator of joint remodeling." (PMID 21062498, 2010).
rheumatoid arthritis (continued). "In contrast to individuals with rheumatoid arthritis (RA), who had high Dkk-1 levels, AS patients showed significantly lower Dkk-1 levels." (PMID 41019055, 2025). "It has been shown that osteoblasts in the vicinity of inflamed joints in rheumatoid arthritis (RA) showed less osteogenic markers while upregulation of Wnt inhibitors DKK1 and Frizzled-related proteins." (PMID 32424558, 2020). "Also, the destructive effect of tumor necrosis factor α (TNFα) on joints in rheumatoid arthritis was found to involve DKK-1, and we have shown that platelet- and endothelial-derived DKK-1 could contribute to vascular inflammation in atherosclerosis." (PMID 23028464, 2012). "Therefore, we hypothesize the synovial expression of TGF-β1 is a differentiating factor for the development of erosive peripheral disease in psoriatic arthritis (TGF-β1 can prime IL-17 A), and synovial expression of Dkk1 may be related to peripheral joint destruction as in rheumatoid arthritis." (PMID 36997896, 2023). "Under inflammatory conditions like rheumatoid arthritis (RA), FLSs have been shown to possess the ability to secrete WNT antagonists such as DKK1 and SOST." (PMID 34250013, 2021). "Nonetheless, clinical studies have shown that DKK1 and FRZB protein expression in serum and/or synovial fluid are expressed at significantly different levels in patients with osteoarthritis or rheumatoid arthritis compared with control." (PMID 24286177, 2013). "The activation of DKK1 expressionby proinflammatory cytokines in rheumatoid arthritis maylead to the suppression of the Wnt signaling pathway and,consequently, the activation of the RANK/RANKL signalingpathway in osteoclasts, increasing their activity and causingthe bone loss characteristic of RA." (PMID 41536794, 2025). "Studies have shown that serum levels of DKK1 are significantly higher in rheumatoid arthritis (RA) patients and are correlated with the severity of the disease, which indicates the possibility that bone erosion in RA may be inhibited by neutralizing the biological activity of DKK1." (PMID 26075259, 2015).
pancreatic cancer (34 papers, 2009 to 2025). "Long noncoding RNA (lncRNA) LINC01133 was shown to methylate the DKK1 promoter, and its upregulation was associated with increased DKK1 methylation and decreased DKK1 expression in pancreatic cancer." (PMID 35355709, 2022). "DKK1, a protein upregulated in human serum, has been recently associated with pancreatic cancer." (PMID 40013338, 2025). "For example, an E‐box motif was identified for Dickkopf‐1 (DKK‐1), an inhibitor of the Wnt/β‐catenin signalling pathway that is elevated in advanced breast and pancreatic cancer patients and is known to promote immune evasion." (PMID 40116596, 2025). "DKK1-SE may be activated in the process of epigenetic reprogramming, and the dysregulation of histone modification caused by abnormal expression of TFs triggers the enhancement of modification of super-enhancers activity, which drives the occurrence and development of pancreatic cancer." (PMID 39107271, 2024). "Based on epigenetic modification and three-dimensional chromatin conformation information, we found a super-enhancer rich in acetylation modification in pancreatic tumors, named DKK1-SE." (PMID 39107271, 2024). "A Dickkopf 1 (DKK1) receptor cytoskeleton-associated protein 4 (CKAP4) has been proposed as a biomarker, which is secreted with exsosomes from pancreatic cancer cells." (PMID 35159011, 2022). "More recently, elevated DKK-1 serum levels and protein expression were observed in a variety of tumor entities (e.g., gastric, breast, ovarian, and pancreatic cancer)." (PMID 34944992, 2021). "For instance, CKAP4 is a receptor for Dickkopf-1 (DKK1) proteins and is also a potential molecular marker of pancreatic cancer." (PMID 34671013, 2021). "Serum DKK1 levels are also significantly higher in lung, esophageal, and pancreatic cancer patients than in healthy controls." (PMID 34117362, 2021). "Another study showed CKAP4 not only regulated the migration of pancreatic cancer cell by relying on DKK1, but also mediated integrin trafficking independently of DKK1." (PMID 33614703, 2020). "On the other hand, CKAP4 mediated integrin trafficking independently of DKK1 and affected pancreatic cancer cell migration." (PMID 33614703, 2020). "A previous study showed a direct influence of GATA6 on DKK1 and thus on Wnt regulation in pancreatic carcinoma." (PMID 32075129, 2020). "For instance, DKK1 was overexpressed in pancreas carcinoma and non-small cell lung cancer where it promotes cancer cells to migrate, invade and proliferate." (PMID 31285694, 2019). "In 42 primary pancreatic tumors the RNA-expression of the FLI1 targets DKK1, INPP5D, IGFBP3 and additionally two members of the Wnt/β-catenin pathway, namely BCL9 and BCL9L, was investigated using quantitative real time PCR." (PMID 27539223, 2016). "Forced overexpression of DKK1 antagonized the effects of GATA6 on Wnt signaling in pancreatic cancer cells." (PMID 21811562, 2011). "To determine the extent to which DKK1 expression affects canonical Wnt signaling in pancreatic cancer, we silenced DKK1 expression in Panc1, Hs766t and A10.7 cells with high endogenous levels of DKK1 expression." (PMID 21811562, 2011). "Moreover, a strong correlation was also found between DKK1 and MDSCs, where DKK1 targeted β-catenin in MDSCs in pancreatic cancer." (PMID 35800432, 2022). "The current review study identifies 22 IHC biomarkers as diagnostic tools for pancreatic cancer that embrace: Pentraxin-3, ENO1, REG4, POSTN, CA125, CA242, Galectin-1, Galectin-9, Maspin, pVHL, MUC1, MUC5AC, THBS2, LTBP2, CPA4, IMP3, CD13, Dkk1, KOC, S100P, Mesothelin, PAM4." (PMID 34988027, 2021). "Based on D’Amico, serum DKK1, although not always tumor-expressed, was associated with tumor expression in pancreatic cancer model." (PMID 31830954, 2019). "Furthermore, there was the significant difference between serum DKK1 levels in patients with early-stage pancreatic cancer (stages I/II) and those in healthy controls (P < 0.001)." (PMID 26101916, 2015).
pancreatic cancer (continued). "In addition, eight patients with stage I pancreatic cancers showed elevated DKK1 levels in conjunction with normal CA19-9 serum levels (Data not shown)." (PMID 26101916, 2015). "Furthermore, N-Myc downstream-regulated 1(NDRG1) and DNA protein cross-link (DpC) reduced cross-talk between pancreatic cancer cells and pancreatic stellate cells by inhibiting β-catenin and YAP/TAZ nuclear localization and promoting DKK1, a Wnt inhibitor, in pancreatic cancer cells." (PMID 36550571, 2022). "Nevertheless, the overexpression of both DKK1 and DKK4 has been observed in pancreatic cancers and proposed as potential therapeutic targets." (PMID 39245631, 2025). "DKK1 is considered a promising biomarker for the early diagnosis and prediction of pancreatic cancer and can be used by WGCNA to screen for key pancreatic cancer targets." (PMID 38305809, 2024). "Intriguingly, a previous study showed that DKK1 and FOXM1 can form a positive feedback loop that promotes cell growth in esophageal squamous cell carcinoma and pancreatic cancer." (PMID 39466790, 2024). "To further confirm the efficacy of SEMet genes in pancreatic cancer metastasis, we examined the protein expression of EMT markers after TGM2 or DKK1 knockdown in two metastasis lesion-originated cell lines, CFPAC-1 and Patu 8988t." (PMID 37351165, 2023). "Given that ORI could activate GSK3β activity and up-regulate the expression of DKK1 in human osteosarcoma, the anti–migratory effect of ORI on pancreatic cancer cells might result from targeting Wnt/β–catenin signalling." (PMID 27453691, 2016). "Moreover, either DKK1 or CKAP4 knockdown suppressed cell growth in vitro and xenograft tumor formation via the Akt signaling pathway, and anti-CKAP4 antibody has also been demonstrated to show an antitumor effect in pancreatic cancer cells." (PMID 40282454, 2025). "The present study, however, did not confirm a high expression of DKK1 in pancreatic tumors." (PMID 27539223, 2016). "There were three proteins (COL10A1, DKK1, and TCN1) with no information in HPA; thus, it is not possible to report about the protein expression in pancreatic cancer." (PMID 32005189, 2020).
osteosarcoma (33 papers, 2007 to 2025). A usually aggressive malignant bone-forming mesenchymal neoplasm, predominantly affecting adolescents and young adults. "Although the signaling mechanisms by which Sema3A affects bone cell differentiation and function are yet to be fully characterised, we present evidence to suggest that DKK1/β-catenin signalling may be one mechanism by which Sema3A influences osteosarcoma-associated ectopic bone formation." (PMID 29720701, 2018). "Studies also noted elevated Dkk-1 expression at tumor margins, correlating with invasiveness; Dkk-1 blockade inhibited osteosarcoma cell proliferation via activation of the WNT/β-catenin pathway." (PMID 41383602, 2025). "A study on osteosarcoma demonstrated that DKK-1 induced cancer stem cell-like properties by shifting the balance of WNT signaling in favor of the non-canonical WNT/JNK signaling." (PMID 38067123, 2023). "In osteosarcoma and adjacent tissues, DKK1 expression was negatively correlated with miR-107 (p = 0.01)." (PMID 35355709, 2022). "TTN-AS1 upregulates Dickkopf Wnt signaling pathway inhibitor 1 (DKK1) to facilitate osteosarcoma progression by competitively binding to microRNA-376a." (PMID 34903127, 2021). "The detection of cell viability using CCK8 methods clearly demonstrated that DKK1 overexpression reversed the promotion effect of PADI4 on osteosarcoma cell proliferation." (PMID 34055985, 2021). "For example, DKK1 antibody restored β-catenin-dependent Wnt signaling and promoted phenotype differentiation in osteosarcoma, leading to less distant metastases." (PMID 34093545, 2021). "Continued parathyroid hormone treatment decreases Dkk-1 mRNA levels in rat osteosarcoma cells in culture." (PMID 31477034, 2019). "Together, these results implicate the autocrine DKK1/GSK3β/β-catenin signaling in the regulation of osteoblast differentiation by osteosarcoma-derived Sema3A." (PMID 29720701, 2018). "The aim of the study was to explore the effects of microRNA-107 (miR-107) by targeting Dkk-1 on osteosarcoma (OS) via the Wnt/β-catenin signaling pathway." (PMID 28682874, 2017). "In striking contrast, there are several reports of dickkopf-1 (DKK-1), also a Wnt signaling antagonist, possibly playing a pro-tumorigenic role in osteosarcoma." (PMID 27049730, 2016). "In this work we investigated the effect of anti-DKK-1 antibodies on the growth and metastasis of patient-derived osteosarcoma xenografts." (PMID 27049730, 2016). "In conclusion, in this work we report the effect of anti-DKK-1 antibodies on the growth and metastasis of patient-derived osteosarcoma xenografts." (PMID 27049730, 2016). "Although the role of Wnt signaling in the pathogenesis of osteosarcoma is controversial, there are several reports of dickkopf-1 (DKK-1), a Wnt signaling antagonist, possibly playing a pro-tumorigenic role." (PMID 27049730, 2016). "Recently, DKK-1 was reported to mediate tumour survival in osteosarcoma cells, via the stress response enzyme ALDH1." (PMID 25182503, 2014). "To examine a potential osteoinhibitory role of Dkk-1 in osteosarcoma (OS), we measured serum Dkk-1 in paediatric patients with OS (median age, 13.4 years) and found it to be significantly elevated." (PMID 17987039, 2007). "Another study demonstrated that DKK1 upregulation could accelerate the deterioration of bone microstructure related to the occurrence of femoral head necrosis and osteosarcoma." (PMID 36686667, 2022). "In osteosarcoma, Dkk1 was considered as molecule with pro-tumor function." (PMID 34828292, 2021). "Notably, the WNT-antagonist DKK1 has been proposed to enhance pro-tumorigenic properties in osteosarcoma, in part through the upregulation of ALDH1A150." (PMID 27292183, 2016). "Given that high levels of Dkk-1 are also expressed by rapidly dividing osteosarcoma (OS) cells in vitro, we measured the level of Dkk-1 in the serum of paediatric patients with OS (median age, 13.4 years) and found it to be significantly elevated when compared with healthy controls." (PMID 17987039, 2007).
osteosarcoma (continued). "However, a study using a mouse model of subcutaneous osteosarcoma xenografts, aiming to determine the linkage between tumor growth velocity and DKK1 level, reported a statistically significant decrease in tumor growth velocity in mice treated with BHQ880 compared with control mice." (PMID 35355709, 2022). "Our work supports further clinical investigation with agents that antagonize DKK-1 signaling and holds out hope that drugs can be developed to specifically target metastasis, finally addressing the major clinical event that limits our ability to cure every patient with osteosarcoma." (PMID 27049730, 2016). "In order to further confirm the role of DKK1 in PADI4-mediated osteosarcoma cell proliferation, we transfected osteosarcoma cells with DKK1 plasmid together with PADI4 overexpression." (PMID 34055985, 2021). "miR-107 targets DKK1, while the expression of this Wnt/β-catenin signaling antagonist is negatively correlated with the levels of miR-107, LRP5, and β-catenin in osteosarcoma tissues." (PMID 34831180, 2021). "This same group noted elevated serum DKK-1 levels in osteosarcoma patients, and using immunohistochemistry demonstrated high levels of DKK-1 expression in human osteosarcoma samples, concentrated at the proliferative, invading edge of tumors." (PMID 27049730, 2016). "Treatment with the anti-DKK-1 antibody, BHQ880, slowed the growth of orthotopically implanted patient-derived osteosarcoma xenografts and inhibited metastasis." (PMID 27049730, 2016). "Moreover, one study integrating scRNA-seq, microarray, and bulk RNA-seq data identified tumor stem cell-related genes associated with survival, TME, and immune infiltration status in osteosarcoma, such as CKLF, DKK1, and Myc." (PMID 39324133, 2024). "We therefore investigated whether site of implantation could affect our ability to detect DKK-1 in the serum of tumor-bearing mice and whether BHQ880 affects the growth of osteosarcoma PDX implanted in an orthotopic location." (PMID 27049730, 2016). "Our work suggests that BHQ880, a monoclonal antibody against the Wnt signaling inhibitor, DKK-1, might be such a drug, and that circulating DKK-1 may be a biomarker of osteosarcoma." (PMID 27049730, 2016). "In mouse osteosarcoma cells, Dkk-1 has been recently shown to activate ALDH1 via the non-canonical Jun-mediated Wnt pathway, which however is not affected in our human CRC cells." (PMID 25788273, 2015). "Likewise, treatment with the anti-Dickkopf 1 (DKK1, antagonist of the Wnt/β-catenin signaling pathway), BHQ880, reduces osteosarcoma development and lung metastasis in mouse models of patient-derived osteosarcoma xenograft, supporting a tumor suppressor role of β-catenin in osteosarcoma." (PMID 34062831, 2021).